CASC15 (cancer susceptibility 15)
Synonyms: lnc-SOX4-1; LOC105374971; formerly LINC00340
Gene: Long non-coding RNA gene on chromosome 6 (21,664,164 to 22,660,021, forward strand). Ensembl gene ENSG00000272168.
Diseases named in the same sentence as CASC15 in open-access papers:
CASC15 is named in the same sentence as 55 diseases in open-access papers, as found by Europe PMC text mining. Sharing a sentence is not in itself a finding about the gene and the disease. The quoted sentences say what the papers report.
neuroblastoma (28 papers, 2015 to 2026). Neuroblastoma (NB) is the most common solid, extracranial childhood tumor. "A research consisting of 118 cases and 281 healthy controls confirmed that CASC15 polymorphisms significantly reduced the risk of neuroblastoma among Chinese children." (PMID 32329235, 2020). "CASC15 lncRNA resides within this locus, and an SNP, rs6939340, which is present in the intron region of the CASC15 lncRNA gene, is associated with the increased risk of neuroblastoma, particularly high-risk neuroblastoma." (PMID 31920530, 2019). "One of the loci, 6p22.3, harbors the CASC15 gene, and variants within this gene is associated with the progression of neuroblastoma." (PMID 31920530, 2019). "In one study, lower expression of one of the variants of CASC15 was correlated with poor prognosis in neuroblastoma patients, while, in contrast, we observed a higher expression in neuroblastoma samples." (PMID 31920530, 2019). "Previous research shows that lncRNA CASC15 is implicated in the biological behaviors of several cancers such as neuroblastoma and melanoma." (PMID 29489064, 2018). "Larger and multicenter-based case-control studies are warranted to further confirm the role of CASC15 gene polymorphisms in decreasing neuroblastoma risk and determine the molecular mechanism of action." (PMID 29207648, 2017). "CASC15 is a cancer susceptibility candidate with SNPs significantly associated with aggressive neuroblastoma." (PMID 29033906, 2017). "To strengthen the conclusion, we further analyzed the association between CASC15 gene polymorphisms and neuroblastoma risk by combining the study populations from Henan province and Guangdong province." (PMID 29207648, 2017). "In this study, we evaluate the association between CASC15 gene polymorphisms and neuroblastoma risk in two combined cohorts of neuroblastoma patients from Northern China." (PMID 29207648, 2017). "Decreased levels of a short isoform of CASC15 associate with poor prognosis and advanced neuroblastoma and downregulation of this isoform increases cell growth and migration." (PMID 29033906, 2017). "In this case-control study, we analyzed the association between three single nucleotide polymorphisms (SNPs) in the CASC15 gene (rs6939340 A>G, rs4712653 T>C, and rs9295536 C>A) and neuroblastoma susceptibility in the Guangdong and Henan populations of China." (PMID 29207648, 2017). "In our previous study, we reported that CASC15 gene polymorphisms were associated with neuroblastoma risk in Southern Chinese population." (PMID 29207648, 2017). "In summary, our results showed the protective role of three CASC15 gene polymorphisms in neuroblastoma susceptibility in two independent populations in China." (PMID 29207648, 2017). "LINC340 also known as Cancer Susceptibility Candidate 15 (CASC15) have likewise been implicated in other diseases including melanoma and neuroblastoma." (PMID 27965463, 2017). "Yet, only four studies have assessed the association of polymorphisms in CASC15 gene with neuroblastoma risk." (PMID 29207648, 2017). "In the current case-control study, we investigated the potential association between CASC15 gene polymorphisms and neuroblastoma risk in two distinct populations from China." (PMID 29207648, 2017). "Three SNPs were identified in the CASC15 gene that associated with clinically aggressive neuroblastoma." (PMID 29207648, 2017). "In the first GWAS carried out in European descent with a total of 1752 neuroblastoma cases and 4171 controls, three SNPs in the CASC15 gene were found to be associated with increased neuroblastoma risk." (PMID 27009839, 2016). "The 6p22.3 locus containing the long intergenic non-coding RNA gene LINC00340 (also known as FLJ22536 and CASC15) is gene poor yet has previously shown association with aggressive neuroblastoma in GWAS studies." (PMID 25367360, 2015).
neuroblastoma (continued). "The differences in the relationship between CASC15 gene polymorphisms and neuroblastoma risk among the two different populations might be ascribed to different environmental exposures as well as different genetic backgrounds." (PMID 29207648, 2017). "CASC15 is a long non-coding RNA (lncRNA) that is highly expressed in various cancers, particularly in melanoma, neuroblastoma, and gastrointestinal cancers." (PMID 40932351, 2026). "Module 9 is highly specific in the undiffNPC cluster and includes several cancer-associated long non-coding (lnc) RNA genes (CASC15, NFIA-AS2, LINC01748, LINC00689, DNAJC27-AS1, and FEZF1-AS1) that are expressed in neuroblastoma, glioma, and other cancers." (PMID 40912258, 2025). "Another lncRNA that displays context-specific function as an oncogene or tumor suppressor is CASC15, which has been shown to act as an oncogene in skin cancers whereas as a tumor suppressor in the context of Neuroblastoma." (PMID 36230680, 2022). "CASC15 was firstly identified as a pivotal tumor suppressor in neuroblastoma but was later reported to play an oncogenic role in many other cancer types, such as melanoma, gastric cancer, liver cancer, lung cancer, and acute leukemia." (PMID 33407675, 2021). "Ensemble annotation predicted six CASC15 lncRNA isoforms, two of which (CASC15-003 and CASC15-004) are widely expressed in neuroblastoma, predicting an improved clinical outcome with increased expression." (PMID 32366932, 2020). "CASC15 (cancer susceptibility 15; previously annotated as LINC00340) is a lncRNA with reported tumour suppressor properties in melanoma, neuroblastoma and acute leukaemia, which is also associated with higher survival probability in AML." (PMID 31870430, 2019). "The CASC15 lncRNA is transcribed in an antisense manner with another non-coding gene NBAT1, which is also associated with neuroblastoma progression." (PMID 31920530, 2019). "Recent data shows that CASC15 and NBAT1 promote differentiation by interactions with SOX9 and USP36, located on chromosome 17q that is frequently gained in high-risk neuroblastomas." (PMID 30760980, 2019). "SNPs in CASC15, LMO1, and LIN28B are enriched in high-risk neuroblastoma and are correlated with neuroblastoma tumor aggressiveness." (PMID 29678897, 2018). "These lncRNAs are well studied in cancer: FENDRR for its prognostic value and its involvement in gastric cancer metastasis and CASC15 for its regulation of SOX4 in RUNX1-rearranged leukemia and harboring a risk SNP for susceptibility of neuroblastoma." (PMID 29757368, 2018). "SNPs in BARD1, cancer susceptibility candidate 15 (CASC15), and LMO1 genes were enriched in high-risk neuroblastoma patients." (PMID 29207648, 2017). "The reported SNPs at previously identified neuroblastoma susceptibility loci, including 2q35 (BARD1), 6p22.3 (CASC15), and 11p15.4 (LMO1) were also nominally associated with 11q deletion." (PMID 28924153, 2017). "These two studies suggest somewhat different roles for CASC15, with an anti-proliferative phenotype in neuroblastoma, but a pro-metastatic role in melanoma." (PMID 28724437, 2017). "Results showed that, CASC15, one lncRNA that was firstly identified as a tumor suppressor in neuroblastoma but was later reported to play an oncogenic role in melanoma, was significantly upregulated in NSCLC compared with matched adjacent normal tissues (p < 0.001)." (PMID 33407675, 2021). "However, the understanding of the functional role of CASC15 and its plausible role in neuroblastoma is still in its preliminary stage." (PMID 31920530, 2019). "CASC15 was recently described in two other types of cancer: neuroblastoma and melanoma." (PMID 28724437, 2017). "Previous GWASs have discovered several inherited common variants in some chromosomal regions that are significantly associated with the risk of neuroblastoma, such as LINC00340 (also known as FLJ22536 or CASC15) at 6p22, BARD1 at 2q35, and LIM domain only 1 (LMO1) at 11p15." (PMID 27009839, 2016).
neuroblastoma (continued). "CASC15 is involved in the manipulation of biological processes in various diseases, which could be a new potential biological therapeutic target, as its abnormal down-expression has been found in ovarian cancer, glioma, and neuroblastoma." (PMID 36482360, 2022). "Cancer susceptibility 15 (CASC15) and neuroblastoma associated transcript 1 (NBAT1) are tumor suppressors that are located at the NB risk-associated 6p22.3 locus." (PMID 31480503, 2019). "These lncRNAs include CASC15 (alias LINC00340) and NBAT1 (alias CASC14), and their role in neuroblastoma carcinogenesis has been further elucidated." (PMID 31920530, 2019). "Thus, SOX9 appears to be one of the key genes in neuroblastoma progression, whose oncogenic functions are controlled by NBAT1 and CASC15-003." (PMID 36230680, 2022). "Out of these lncRNAs, CASC15 and CTD-2881E23.2 were significantly upregulated in both DTCs and tumor and hence could be more important in the progression of neuroblastoma." (PMID 31920530, 2019). "CASC15 clearly exhibited only active histone marks but not the repressed state, which represents its transcriptional state in neuroblastoma." (PMID 31920530, 2019). "After this cross-sectional study, we were able to identify three significant lncRNAs, CASC15, PPP1R26-AS1, and USP3-AS1, which could serve as potential biomarkers in clinical studies of neuroblastoma pathogenesis." (PMID 31920530, 2019).
melanoma (24 papers, 2016 to 2026). A malignant, usually aggressive tumor composed of atypical, neoplastic melanocytes. "Overexpression of CASC15 is also associated with the progression and phenotype switching of melanoma." (PMID 31920530, 2019). "Interestingly, a second study demonstrated that CASC15 was associated with metastatic melanoma and siRNA-mediated knockdown resulted in altered growth and metastatic properties of melanoma-derived cell lines." (PMID 28724437, 2017). "Overexpression of CASC15 has also been implicated in melanoma progression and metastasis." (PMID 27539887, 2016). "CASC15 is an intergenic lncRNA, and small interfering knockdown experiments have shown that CASC15 contains tumour-promoting properties in melanoma cell lines, and we find greater expression of CASC15 is associated with human muscle growthin vivo." (PMID 39669123, 2024). "It has been demonstrated that knockdown of CASC15 in melanoma cells inhibits Wnt/β-catenin signaling pathway, which results in decreased proliferation, invasion, and migration, as well as increased cell apoptosis." (PMID 37325482, 2023). "CASC15 depletion represses proliferation, induces apoptosis and decreases invasion in melanoma cells and tumor growth in vivo, and this effect has been impaired after PDCD4 knockdown." (PMID 37325482, 2023). "ANRIL and CASC15, which were documented to be overexpressed and had oncogenic role in melanoma, were also up-regulated in primary melanoma in our microarray data." (PMID 35096622, 2021). "Numerous studies have demonstrated that CASC15 expression is elevated in a variety of human malignancies, such as melanoma, gastric cancer, liver cancer, and acute leukemia." (PMID 33407675, 2021). "Analysis of the 10-year disease-free survival rates and CASC15 expression in stage III melanoma lymph node metastases revealed that patients with high CASC15 expression had a significantly reduced DFS." (PMID 28350340, 2017). "A long intergenic non-coding RNA, CASC15, correlates with melanoma progression and is involved in the regulation of phenotype-switching." (PMID 28225791, 2017). "Furthermore, CASC15 correlates with β-Catenin expression in melanoma, promoting melanoma progression through activation of the Wnt/β-Catenin signaling pathway." (PMID 39519092, 2024). "As CASC15 level has been found increased during melanoma progression, it might be considered as independent predictor of disease recurrence in patients with stage III lymph node metastasis." (PMID 37325482, 2023). "Recently, a novel oncogenic lncRNA, CASC15, is identified in various cancers such as basal cell 13, hepatic 14, 15 and tongue squamous cell carcinoma 16, as well as cervical 17, breast 18, melanoma 19-21, gastric 22, 23, colon 24, lung 25 and ovarian 26 cancer." (PMID 35342355, 2022). "lncRNA CASC15 promotes melanoma progression by epigenetically regulating PDCD4." (PMID 31399501, 2019). "The expression of CASC15 is upregulated in melanoma, hepatocellular carcinoma and gastric cancer." (PMID 31620370, 2019). "Additional in vitro experiments could show that CASC15 regulates melanoma cell phenotype switching between proliferative and invasive states." (PMID 28350340, 2017). "In line with this, other groups have recently reported that CASC15 could promote tumorigenesis by activating Wnt//β-catenin signaling pathway in colon cancer and melanoma, suggesting that CASC15/β-catenin axis has an important and universal function in cancer development and progression." (PMID 33407675, 2021). "The molecular interactions of CASC15 in melanoma is still unknown." (PMID 28415644, 2017). "Regarding circCASC15, it is generated by the CASC15 gene, which produces a long non-coding RNA that facilitates tumour cell proliferation and EMT in vitro but also promotes melanoma and gastric cancer progression in patients." (PMID 38203852, 2024).
melanoma (continued). "PDCD4, a tumor suppressor, was recently demonstrated to be negatively regulated by CASC15, via recruiting EZH2 and subsequently changing H3 K27me3 level in melanoma." (PMID 30519392, 2018). "In melanoma, CASC15 may recruit EZH2, and EZH2 could subsequently directly bind to the promoter of PDCD4 in melanoma cells and inhibit PDCD4 expression." (PMID 31620370, 2019). "Several studies have identified known lncRNAs that are abnormally expressed in melanoma, such as SAMMSON, HOTAIR, SLNCR1, BANCR, SPRY4-IT1, ANRIL, Llme23, UCA1, MALATA1, GAS5, H19, CASC15, PTENP1, and MIR31HG." (PMID 28225791, 2017).
gastric cancer (10 papers, 2018 to 2025). A primary or metastatic malignant neoplasm involving the stomach. "Knockdown of the CASC15 gene significantly reduced the proliferation and invasiveness of gastric cancer cells." (PMID 40191723, 2025). "Using pull-down analysis with biotin-labeled miR-33a-5p in gastric cancer cells, it was found that miR-33a-5p directly interacted with lncRNA CASC15, establishing its role as a ceRNA for miR-33a-5p64." (PMID 33414456, 2021). "Previous studies have shown that CASC15 plays oncogenic roles in the development and progression of colorectal cancer and gastric cancer." (PMID 31665008, 2019). "It has been reported that overexpression of lncRNA CASC15 contributes to the development of colorectal cancer and gastric cancer, indicating its oncogenic role." (PMID 31665008, 2019). "A previously study has shown that CASC15 overexpression resulted in the promoted proliferation of gastric cancer cells." (PMID 31665008, 2019). "Overexpression of CASC15 has been observed in colorectal cancer and gastric cancer." (PMID 31665008, 2019). "Here, we hypothesized that CASC15‐miR‐33a‐5p‐CDKN1A/ZEB1 axis would be a novel pathway in gastric cancer." (PMID 29489064, 2018). "Besides, lncRNA CASC15 was found to promote EMT in gastric cancer by targeting ZEB1." (PMID 33292221, 2020). "CASC15 promotes EMT, and CASC15 overexpression is closely related to gastric cancer invasion and metastasis by regulating the CASC15/miR-33a-5p/ZEB1 pathway." (PMID 40191723, 2025). "RT-PCR and Western blot analyzes proved that the inhibition of lncRNA CASC15, as well as the induced expression of miR-33a-5p, reduced levels of Zeb1 expression in AGS and SGC7901 gastric cancer cells." (PMID 33414456, 2021). "Here, we aimed to explore in detail how CASC15 contributes to the growth of gastric cancer (GC)." (PMID 29489064, 2018).
colon cancer (7 papers, 2020 to 2026). "The expression of lncRNA cancer susceptibility 15 (CASC15) is increased in colon tumor tissues and associates with TNM stage and tumor metastasis." (PMID 33246471, 2020). "Likewise, upregulation of lncRNA CASC15 was identified in colon cancer tissues and its expression was significantly correlated with clinical TNM stages." (PMID 36497002, 2022). "In addition, CASC15 inhibition reduces the migration and invasion of colon cancer cells via regulation of the miR-4310/LGR5/Wnt/β-catenin axis." (PMID 33246471, 2020). "In addition, CASC15 knockdown suppresses colon cancer cell proliferation and tumor growth in vitro and in vivo." (PMID 33246471, 2020). "Both CASC15 and CASC21 promoted colon cancer proliferation and metastasis through the activation of the Wnt/β-catenin signaling pathway." (PMID 36497002, 2022). "CASC15 has been observed to regulate the expression of leucine-rich repeat-containing G-protein coupled receptor 5 (LGR5) by targeting miR-4310, thereby activating the Wnt/β-Catenin signaling pathway in colon cancer." (PMID 39519092, 2024).
lung carcinoma (6 papers, 2021 to 2024). "For instance, the lncRNA CASC15 promotes the proliferation and invasion of lung cancer cells via the miR-766-5p/KLK12 axis." (PMID 39588384, 2024). "- miR-766-5p act as tumor suppressor miRNA in lung cancer.- Ectopic expression of lncRNA CASC15 contribute to ling cancer progression by targeting miR-766-5p/KLK12 axis." (PMID 37205191, 2023). "For instance, miR-766-5p suppressed tumor growth in vivo, and miR-766-5p inhibitor attenuated the cancer-promoting effects of si-CASC15 in lung cancer." (PMID 35502885, 2022). "As expected, stable knockdown of CASC15 significantly inhibited tumor growth in nude mice bearing human lung carcinoma xenografts." (PMID 33407675, 2021). "The clinical significance of CASC15 in lung cancer was investigated by Kaplan-Meier survival analysis." (PMID 33407675, 2021). "CASC15 is another unfavorable prognostic marker found in multiple tumors, including lung cancer." (PMID 36105077, 2022). "Meanwhile, CASC15 can promote lung cancer metastasis via miR-766-5p/KLK12 axis." (PMID 34745939, 2021). "In vivo experiments demonstrated that, compared with control groups with stable knockdown of CASC15, concurrent overexpression of SOX4 significantly promoted tumor growth in nude mice bearing human lung carcinoma xenografts." (PMID 33407675, 2021).
osteosarcoma (5 papers, 2021 to 2023). A usually aggressive malignant bone-forming mesenchymal neoplasm, predominantly affecting adolescents and young adults. "In addition, lncRNA CASC15 was shown to be upregulated in osteosarcoma plasma exosomes compared with that in control exosomes, and its expression has been confirmed to predict poor prognosis in human cancers." (PMID 37377390, 2023). "Silencing of CASC15 impairs progression of osteosarcoma cells." (PMID 35765040, 2022). "The exosomal lncRNA CASC15 is overexpressed in osteosarcomas and increases growth and metastasis." (PMID 35765040, 2022). "Further studies show that exosomal CASC15 decreased the expression of miRNA-338-3p by sponging and increases the expression of RAB14 in osteosarcomas." (PMID 35765040, 2022).